POU5F1P5 (POU class 5 homeobox 1 pseudogene 5)
Synonyms: Oct4-pg5
Gene: Processed pseudogene on chromosome 10 (68,010,205 to 68,010,862, reverse strand). Ensembl gene ENSG00000236375.
Diseases named in the same sentence as POU5F1P5 in open-access papers:
POU5F1P5 is named in the same sentence as 3 diseases in open-access papers, as found by Europe PMC text mining. Sharing a sentence is not in itself a finding about the gene and the disease. The quoted sentences say what the papers report.
endometrial cancer (1 paper, 2020). Primary or metastatic malignant neoplasm involving the endometrium (mucous membrane that lines the endometrial cavity). "POU5F1P5 was reported to be upregulated in endometrial cancer specimens, and overexpression of POU5F1P5 promoted the proliferation of endometrial cancer cells." (PMID 32684827, 2020).
cancer (2 papers, 2020 to 2022). A tumor composed of atypical neoplastic, often pleomorphic cells that invade other tissues. "The discrepancy may reflect the difference in cancer types, which, if true, suggests that the function of POU5F1P5 depends on cancer type." (PMID 32684827, 2020). "POU5F1P5 has been reported to be upregulated in various cancer tissues and cancer cell lines, but the function of POU5F1P5 remains unclear." (PMID 32684827, 2020). "Interestingly, two of these OCT4 pseudogenes, POU5F1P5 and POU5F1B, were found to be transcribed in cancer cells." (PMID 35176995, 2022).
tumor (1 paper, 2020). "This is inconsistent with our result that upregulation of POU5F1P5 had tumor suppressor effects in HGSC cell lines." (PMID 32684827, 2020).